FOXO3 (forkhead box O3)
Diseases named in the same sentence as FOXO3 in open-access papers (continued):
Sharing a sentence is not in itself a finding about the gene and the disease.
macular degeneration (1 paper, 2020). Loss of vision in the central portion of the retina (macula), secondary to retinal degeneration. "Life-extending SNPs near APOE, FOXO3 and FGD6 are all associated with increased measures of macular degeneration." (PMID 32678081, 2020).
myasthenia (1 paper, 2024). "In this context, a study involving transgenic mice showed that FOXO1 overexpression in skeletal muscles caused severe myasthenia, with the in vitro and in vivo overexpression of FOXO3 increasing the activity of the Atrogin-1 promoter to further accelerate myasthenia." (PMID 38396627, 2024).
myocarditis (1 paper, 2023). Myocarditis is a condition that is characterized by inflammation of the heart muscle (myocardium). "In this regard, FOXO3 renders cardiomyocytes susceptible to apoptosis stimuli, particularly with respect to DCM risk factors such as genetic perturbations, ischemic injuries, myocarditis and chemical drugs but does not directly trigger cellular apoptosis." (PMID 37138538, 2023).
neuropathy (1 paper, 2024). A disorder affecting the nervous system that manifests with pain, tingling, numbness, and/or muscle weakness. "Chronic CHIKV patients also show upregulation of genes associated with neuronal death (FOXO3, MCL1, ZNF746, and PICALM) and T-cell differentiation, which may contribute to secondary neuropathy symptoms." (PMID 39596565, 2024).
NK/T cell lymphoma (1 paper, 2015). "The deletion of 6q21 has been identified as the common genetic aberration in NK/T cell lymphoma (20–43%), and the genes located in the region of 6q21, including POPDC3, PREP, PRDM1, ATG5, AIM1, HACE1, and FOXO3, were reasonably considered the affected candidates." (PMID 26221594, 2015).
ovarian teratoma (1 paper, 2018). A non-seminomatous germ cell tumor arising from the ovary. "A deficiency of Retinoblastoma 1 (Rb1) or Forkhead box O3a (Foxo3a) has been shown to cause oocyte abnormality and ovarian teratoma." (PMID 29378702, 2018).
Peutz-Jeghers syndrome (1 paper, 2019). An autosomal dominant disorder caused by pathogenic variants in the STK11 gene, characterized by hamartomatous polyps in the gastrointestinal tract, mucocutaneous pigmentation and increased risk of GI and extra-GI malignancies. "These syndromes are characterized by mutations in STK11 (Peutz-Jeghers syndrome, PJS) or PTEN (PTEN hamartoma tumor syndrome, PHTS), which encode for FOXO3 upstream regulators." (PMID 31303978, 2019).
polymyositis (1 paper, 2024). A rare idiopathic inflammatory myopathy characterized by symmetric proximal muscle weakness and elevated muscle enzymes. "The results showed that all the keywords could be categorized into 12 distinct groups, which include FOXO3, m6A modification, immune system, immune infiltration, metabolism, activation, IPEC-J2, DNA methylation, presynaptic, ischemia-reperfusion (i/r), polymyositis and agonist." (PMID 39686999, 2024).
posterior fossa ependymoma (1 paper, 2022). A high grade ependymoma that is located within the posterior fossa. "Interestingly, 6/7 of the constrained genes in which pLoF variants were found in patients with posterior fossa ependymoma show particularly high expression levels in cerebellar tissue (UHRF2, FOXO3, CDC42BPA, ZMYM2, CHD6 and DNAJC2)." (PMID 36008825, 2022).
primary biliary cirrhosis (1 paper, 2025). "In the FoxO3/Bim signaling pathway, FoxO3 made an effect on Bim decreasing, as a result the apoptosis of hepatocytes was decreased in primary biliary cirrhosis in mice." (PMID 39891057, 2025).
retinoblastoma (1 paper, 2022). A malignant tumor that originates in the nuclear layer of the retina. "FOXO3 triggers apoptosis in the absence of survival factors, and low expression of FOXO3 in advanced retinoblastoma indicates the tumor strategy to escape apoptosis." (PMID 36338723, 2022).
scrapie (1 paper, 2014). A fatal disease of the nervous system in sheep and goats, characterized by pruritus, debility, and locomotor incoordination. "We therefore analyzed the expression levels of FOXO3 in targeted secondary Western blots of brainstem-cerebellum homogenates from scrapie-infected mice at 70, 90, 110, 130 dpi or at terminal stages of disease." (PMID 25183307, 2014). "Consistent with the lower expression levels of DLK (two-tailed paired ratio t-test; P = 0.0182), JNK2 (P = 0.0063), and MST1 (P = 0.0095), FOXO3 levels were also significantly lower (P < 0.0001) in the brainstem-cerebellum of scrapie- than of mock-infected mice at 130 dpi." (PMID 25183307, 2014). "However, MST1 and FOXO3 were still expressed to significantly lower levels in the cortical region of scrapie- than of mock-infected mice at 130 dpi (MST1, P = 0.0384; FOXO3, P = 0.0090)." (PMID 25183307, 2014). "The differential expression of MST1 and FOXO3 in the brainstem-cerebellum and cortical region, albeit to differing degrees, supports a model in which MST1/FOXO3 signaling is dysregulated during progression of scrapie." (PMID 25183307, 2014).
soft tissue tumors (1 paper, 2023). "In soft tissue tumors, the shortest paths to HEY1 and FOXO3 had the highest importance." (PMID 37242535, 2023).
tongue squamous cell carcinoma (1 paper, 2021). A squamous cell carcinoma that arises from the tongue. "Such relocalization of FOXO proteins has been associated with aggressive behavior of cancer cells, as 14-3-3ζ-induced nuclear exclusion of FOXO3 resulted in increased proliferation and migration of tongue squamous cell carcinoma cells." (PMID 35008549, 2021). "Another member of the 14-3-3 family (14-3-3ζ) was shown to enhance the migration of tongue squamous cell carcinoma cells through the relocalization of FOXO3 from the nucleus to the cytoplasm." (PMID 35008549, 2021).
uterine cancer (1 paper, 2021). Primary or metastatic malignant neoplasm involving the uterine corpus and/or the cervix. "In addition, the FOXO3a (forkhead box O3A) /eIF4EBP1 (eIF4E binding protein 1) axis plays a critical role in the inhibitory effect of G129R(a prolactin antagonist) on cell proliferation and cell cycle in uterine cancer." (PMID 34922580, 2021).
vascular dementia (1 paper, 2024). A degenerative vascular disorder affecting the brain. "It protects against vascular dementia by reducing MDA levels, inhibiting ROS production, increasing glutathione peroxidase and total thiol levels, and up-regulating Nrf2, FOXO1, FOXO3, and FOXO4, thereby reducing oxidative stress and improving learning and memory functions." (PMID 39169952, 2024).
viral myocarditis (1 paper, 2021). Myocarditis that is caused by an infection with a viral agent. "We showed that Foxo3 plays an important role in acute viral infection as its activation attenuated natural killer (NK) cell responses in a viral myocarditis model." (PMID 33953705, 2021).
tumor (783 papers, 2007 to 2026). "Reduced FOXO3 mRNA expression has been associated with larger tumor size and advanced stages, while activation of this gene has been reported to suppress proliferation." (PMID 41300329, 2025). "Our results suggest that Foxo3 represents another critical anti-tumor mechanism associated with CAPE while confirming that AMPK functions upstream of Foxo3." (PMID 39729481, 2024). "The altered expression and activity of SIRT1 and FOXO3 are closely associated with tumorigenesis and tumor progression in various cancers." (PMID 39266959, 2024). "FOXO3, however, has been associated with tumour suppression, as indicated by studies showing that prevention of FOXO3 inactivation due to nuclear export reduces levels of ibrutinib resistance in DLBCL." (PMID 37275916, 2023). "In UBC, the expression of FOXO3 mRNA in UBC specimens was lower than that in NATs, and a lower FOXO3-positive rate was associated with LN metastasis and a high tumor grade." (PMID 37573356, 2023). "FOXO3 is located on chromosome 6q21 and is protein-encoding gene-regulating aging, apoptosis, and tumor." (PMID 35645813, 2022). "circ-Foxo3 is a circRNA encoded by the tumour suppressor gene Foxo3 that can combine with different proteins to cause different biological effects." (PMID 36393967, 2022). "Berberine can also induce mitochondrial dysfunction by significantly upregulating the expression of FoxO1 and FoxO3, thereby causing tumor cell apoptosis." (PMID 36034426, 2022). "The result showed that the deletion of FOXO1 and FOXO4 genes, and the increase in CNVs in the FOXO3 gene, were linked to tumor progression." (PMID 36555288, 2022). "Exo-LBX1-AS1 secreted from RBPJ-OE Mφ inhibits tumor progression through the LBX1-AS1/miR-182-5p/FOXO3 pathway, and LBX1-AS1 is probably a diagnostic biomarker and potential target for OSCC therapy." (PMID 33816238, 2021). "This study suggested that hsa_circ_0001368 has the potential of sponging miR-6506-5p and this sponging leads to elevating the expression of the tumor-suppressive gene, FOXO3 (associated with apoptosis of tumor cells)." (PMID 35087404, 2021). "Accordingly, it will be important to confirm the tumor suppressor role of FOXO3 by a different approach, such as loss of FOXO3 function model." (PMID 33795838, 2021). "In contrast to the metabolic signatures of FOXO3 low tumors, FOXO3 high tumor samples displayed enrichment for pathways associated with maintenance of stemness and restraint of cell cycle progression." (PMID 36303712, 2021). "Emerging evidence indicates that FOXO3 acts as a tumor suppressor in cancer: FOXO3 is commonly inactivated in cancer cell lines either by cytoplasmic sequestration of FOXO3 protein or by mutation of the FOXO3 gene." (PMID 34073605, 2021). "Several of the hub genes (GATA3, IGF1R, and FOXO3) have been reported to be associated with the tumor progression of ESCC in previous studies." (PMID 33747034, 2021). "In tumor cells with low β-catenin levels, FOXO3 nuclear translocation caused by PKB inhibitor treatment induced apoptosis and reduced tumor growth in vivo." (PMID 34298659, 2021). "The transcription factor FOXO3 has been associated in different tumor entities with hallmarks of cancer, including metastasis, tumor angiogenesis, maintenance of tumor-initiating stem cells, and drug resistance." (PMID 31591479, 2020). "In vivo studies confirmed that FOXO3 deficiency abolished the suppression of MCF7 xenograft tumor growth induced by LINC01355." (PMID 31243265, 2019). "In summary, our research reveals that URRCC functions as a tumor-inducer to control the ccRCC progression via modulating URRCC/EGFL7/P-AKT/FOXO3 positive feedback loop and cause cascading effects in ccRCC." (PMID 30953521, 2019). "Taken together, these data demonstrate that CBX2 upregulation in HGSOC is associated with poorer prognosis, repression of the FOXO3 tumor suppressor, and is possibly linked to chemoresistance." (PMID 30478317, 2018).
tumor (continued). "FOXO3 has been shown to be a novel regulator of the immunological tolerance associated pDCs, and thereby, promotes the immunosuppressive activity of tumour-associated pDCs (TApDCs)." (PMID 29180117, 2018). "The transcription factor FOXO3 is an effective tumor suppressor; dysregulation of FOXO3 is associated with cancer initiation and progression." (PMID 29221208, 2017). "One explanation is that chemotherapy, hypoxia and/or nutrient-deprivation during tumor growth constitute stress signals that cause nuclear accumulation of FOXO3 also in cells with a highly active PKB pathway." (PMID 27769056, 2016). "It underlines a gene-dosage-dependent FOXO3 effect in vivo: Slightly increased activity induces tumor-angiogenesis and vessel permeability, whereas strong activation of over-expressed FOXO3 exposes the “FOXO3 tumor suppressor phenotype”." (PMID 27769056, 2016). "In a final step we therefore transplanted NB15/Ctr and NB15/FOXO3 cells into immune-deficient nude mice and investigated the effect of FOXO3 on tumor growth and tumor vessel formation." (PMID 27769056, 2016). "FOXO3 methylation levels were significantly higher in BRCA1-mutated tumours compared with BRCA2, BRCAx (non-BRCA1/2) and non-BRCA1-mutated (BRCA2/x) tumours." (PMID 27043660, 2016). "We conclude from our study that in high-stage NB patients, FOXO3 contributes to tumor cell longevity associated with death resistance and increased tumor vascularization." (PMID 27769056, 2016). "Loss of function of FOXO3 through phosphorylation has been linked to tumorigenesis and poor patient survival in cancer, suggesting that FOXO3 is a key tumor suppressor." (PMID 20625400, 2010). "It is crucial to elucidate the molecular mechanisms underlying the ubiquitin-mediated degradation of FOXO3 tumor suppressor." (PMID 20625400, 2010). "Notably, we found FOXO3 to be the most frequently mutated gene among those tested, with significant implications for tumour biology." (PMID 41007296, 2025). "Subtype‐specific circRNAs are also noted: circEGFR was upregulated in triple‐negative subtype and aligned with aggressive clinical features and reduced chemotherapy sensitivity, whereas circ‐FOXO3 was downregulated and associated with lymph‐node metastasis, consistent with a tumor‐suppressive role." (PMID 40965819, 2025). "Considering the tumor suppressing function of FOXO3, rs17069665 and rs4946936 might influence RMS risk and prognosis via regulating the expression of FOXO3 by altering the bindings to MYC, CTCF and/or RELA." (PMID 38720807, 2024). "According to their study, circ-Foxo3 expression was not only significantly associated with tumor size and histologic grade but was also related to wild-type isocitrate dehydrogenase (IDH) expression and O6-methylguanine DNA methyltransferase (MGMT) methylation status." (PMID 33833780, 2021). "Although further investigations are required, our systematic review with meta-analysis demonstrated the promising value of FOXO3 as a novel biomarker for HCC, revealing that high FOXO3 expression is significantly correlated with tumor development, shorter survival rate and the risk of invasion." (PMID 34771514, 2021). "Among these, the transcription factor FOXO3 is of particular interest since it has been shown that the association between 14-3-3 proteins and FOXO3 triggers the nuclear export of FOXO3, leading to the inhibition of its tumor suppressor functions, such as the repression of EMT mediators." (PMID 35008549, 2021). "Notably we observed that high expression of CBX2 correlated to a loss of an active tumor suppressor, FOXO3." (PMID 30478317, 2018). "The tumor suppressor gene FOXO3 encodes two ncRNAs, the pseudogene Foxo3P and circ-Foxo3, both of which may act as miRNA sponges." (PMID 29349062, 2017). "The loss of FoxO3 may also be affecting other tumour-suppressive functions for which FoxO1/4 cannot fully compensate." (PMID 26764572, 2016).
tumor (continued). "Although our data suggest a role for FoxO3-mediated inhibition of apoptosis in restraining Myc-driven tumour development, we suspect that loss of FoxO3 may also be affecting other tumour-suppressive functions for which FoxO1/4 cannot fully compensate." (PMID 26764572, 2016). "This post-translational modification causes inhibition of FOXO3 tumor suppressor activity." (PMID 24349301, 2013). "In addition, the dose of 500 μg 4OHT/mouse may cause full activation of ectopic FOXO3, thereby better exposing the “tumor suppressor phenotype” as also observed in vitro." (PMID 27769056, 2016). "In vivo, the impact of FOXO3 knockdown on tumor growth under irradiation was evaluated using A549-RR xenografts." (PMID 41888517, 2026). "In vivo, FOXO3 knockdown markedly suppressed A549-RR tumor growth and improved radiotherapy response." (PMID 41888517, 2026). "Previous studies have reported the downregulation of FOXO3 in various cancers, where it acts as a tumor suppressor." (PMID 40589632, 2025). "They orchestrate LD formation within tumor tissues via intricate pathways linked to inflammation, hypoxia, and acidosis, intersecting with key oncogenic pathways like PTEN, KRAS, and FOXO3/Sirtuin6." (PMID 41041279, 2025). "MiR-27a reduces SPRY2 and FOXO3 in U87 GB cells, but the inhibition of miR-27a impairs the proliferation of U87 cells and the tumor growth of U87 cells in subcutaneous mouse tumor xenografts, in which SPRY2 and FOXO3 are increased." (PMID 41516252, 2025). "The overexpression of miR-155 not only downregulates critical tumour suppressor genes, such as FOXO3 and CDKN1B, but also plays a well-documented pro-fibrotic role in various fibrotic conditions by promoting the synthesis of ECM proteins, including collagen." (PMID 41007812, 2025). "ERK can also influence FOXO1 and FOXO3 transcription factors, which control the expression of several tumor suppressor genes." (PMID 41462911, 2025). "Given the pivotal role of Wnt signaling activation in PC metastasis, LINC00261’s ability to restore FOXO3 expression and suppress this pathway highlights its broader tumor-suppressive potential." (PMID 40136629, 2025). "Further investigation revealed that tumor-derived 3′tiRNA-AlaCGC induces fibroblast senescence by suppressing the expression of FOXO3." (PMID 40855047, 2025). "Our further investigation revealed that tumor-derived 3′tiRNA-AlaCGC induces fibroblast senescence by suppressing the expression of FOXO3, restoring FOXO3 expression in HFL1-mimic cells can reverse the senescence phenotype." (PMID 40855047, 2025). "An example of this is circ-FOXO3, which was found to have decreased expression in tumor cell lines and tumor tissues compared to adjacent tissues." (PMID 40141179, 2025). "This inhibition leads to FOXO3 accumulation and subsequent suppression of PD‐L1 transcription in tumor cells." (PMID 40798865, 2025). "This inhibitory effect of FOXO3 overexpression on tumor growth was diminished by downregulation of SPRY2, confirming the important interplay between FOXO3, miR-21, and SPRY2 in NB." (PMID 41516252, 2025). "Mechanistically, PLUM interacts with Polycomb Repressive Complex 2 to regulate its stability and histone methyltransferase activity, modulating the expression of tumor suppressor genes, FOXO3 and ZFP36, to activate the unfolded protein response (UPR)." (PMID 40890111, 2025). "Phosphorylation of the Forkhead Box O1 (FOXO1) and O3 (FOXO3) transcription factors at positions T24 and T23, respectively, renders these proteins to act as tumor suppressors and play a role in regulating fibrosis." (PMID 41373844, 2025). "Downregulation of tumor suppressors, such as FOXO3 and IRF1, and increased FOXP3 and pAKT1, were observed." (PMID 40924302, 2025). "At the molecular level, circ‐FOXO3 acts as a tumor suppressor by interacting with Wolf‐Hirschhorn syndrome candidate 1 (WHSC1)." (PMID 40965819, 2025).